AQP4 (aquaporin 4)
Diseases named in the same sentence as AQP4 in open-access papers (continued):
Sharing a sentence is not in itself a finding about the gene and the disease.
COVID-19 (17 papers, 2021 to 2026). A disease caused by infection with severe acute respiratory syndrome coronavirus 2. "We perform a comparative analysis to examine the influence of COVID-19 on the development of MOG-ON and AQP4-ON, as well as to identify distinctive features associated with COVID-19-related ON." (PMID 38988608, 2024). "After excluding these SNPs, the causal association of COVID-19 susceptibility with AQP4+NMOSD remained nominally significant (IVW: OR = 5.090, 95% CI: 1.151-22.505, P = 0.032)." (PMID 37575255, 2023). "The MR results demonstrated a nominal association between COVID-19 susceptibility and the risk of AQP4+ NMOSD, as evidenced by the IVW method (OR = 4.958; 95% CI: 1.322-18.585; P = 0.018)." (PMID 37575255, 2023). "In conclusion, we provide strong evidence supporting the genetic liability to COVID-19 susceptibility was positively associated with the high risk of AQP4+ NMOSD." (PMID 37575255, 2023). "Our findings provide compelling evidence for a causal effect of COVID-19 phenotype on AQP4+ NMOSD, shedding new light on the understanding of the comorbidity between COVID-19 and NMOSD." (PMID 37575255, 2023). "Our study found the causal effect of COVID-19 susceptibility on AQP4+NMOSD, which supports previous observational findings." (PMID 37575255, 2023). "In this MR study, our findings showed that genetically predicted COVID-19 susceptibility was associated with a high risk of AQP4+ NMOSD." (PMID 37575255, 2023). "So far two cases of AQP4-antibody positive NMOSD have been reported in association with viral vector COVID-19 vaccines." (PMID 35585528, 2022). "A synthesis of currently reported COVID-19-associated ON cases reveals several consistent trends: we found that MOG-ON was the most common subtype among COVID-19-associated ON cases, while AQP4-ON remained rare and the majority of patients had favorable outcomes." (PMID 40728559, 2025). "Mild COVID-19 is more likely associated with MOG-ON than AQP4-ON." (PMID 38988608, 2024). "Interestingly, genetic liability to COVID-19 susceptibility was nominally associated with AQP4+NMOSD by implementing the IVW approach (OR = 4.958, 95% CI: 1.322-18.585, P = 0.018), consistent with MR Egger, weighted median and weighted mode." (PMID 37575255, 2023). "In this study, we still included 73 patients with seronegative AQP4-IgG, who might have different pathogenesis, treatment response, and susceptibility to and severity of COVID-19 from those with seropositive AQP4-IgG." (PMID 33828524, 2021). "In our review of 35 published COVID-19-associated ON cases, MOGAD accounted for over half (51.4%), whereas only one case (2.86%) was identified as AQP4-ON." (PMID 40728559, 2025). "In this retrospective cohort study, COVID-19-associated ON was characterized by a higher incidence of ADEM-ON and lower AQP4-ON compared to pre-pandemic cases." (PMID 40728559, 2025). "Phenotypically, hypertrophic astrocytes with lower branching complexity and co-expression of GFAP/collagen IV and aquaporin 4 (AQP4) were observed in COVID-19 patients." (PMID 39451987, 2024). "This scarcity results in limitations in multivariate analyses aimed at ruling out confounding factors, establishing a causal link between COVID-19 and MOG-ON/AQP4-ON, and understanding the underlying pathogenesis and prognosis." (PMID 38988608, 2024). "In terms of history of preceding infection, a higher proportion of MOG-ON patients reported a history of COVID-19 or other infections within 6 weeks prior to the onset of ON compared to the AQP4-ON group (19/26 [73.1%] vs. 6 /20 [30%]; p = 0.007)." (PMID 38988608, 2024). "The mean time from COVID-19 to ON onset was shorter in patients with MOG-ON compared to patients with AQP4-ON (6.87 ± 6.25 weeks vs. 11.06 ± 5.84 weeks; p = 0.038), indicating a closer temporal association between MOG-ON onset and COVID-19." (PMID 38988608, 2024).
COVID-19 (continued). "Using a contingency table chi-square test, the results showed that there was a significantly higher proportion of patients with MON-ON developing symptoms within 6 weeks after COVID-19 compared to those with AQP4-ON (15/23 [65.2%] vs. 5/17 [29.4%]; p = 0.025)." (PMID 38988608, 2024). "This makes it difficult to determine the exact association between COVID-19 and both MOG-ON and AQP4-ON, as well as their actual prevalence and distinctive characteristics." (PMID 38988608, 2024). "COVID-19 astrocytes also showed lower levels of Aquaporin-4 (AQP4), and Metallothionein-3 in subsets of COVID-19 brain regions." (PMID 37483351, 2023). "Other individuals have developed MRI manifestations consistent with NMOSD and positive AQP4 IgG after receiving the COVID-19 vaccine." (PMID 37575255, 2023). "The COVID-19 vaccinated group was also more likely to present with positive AQP4 antibodies than the SARS-CoV-2 infected group (85% vs. 65%)." (PMID 37426444, 2023). "In patients who had died of COVID-19, there was decreased expression of AQP4 in the ventral ION compared to the ARDS patients." (PMID 37483351, 2023). "A future larger-scale study is necessary to explore the occurrence of COVID-19 in NMOSD patients with seronegative AQP4-IgG." (PMID 33828524, 2021). "In COVID-19-associated ON, all serum samples were negative for AQP4 and GFAP antibodies, four (33.3%) patients were MOG-IgG-positive (titres were 1:100 in three patients and 1:32 in one patient), and one patient was CRMP5-IgG-positive (titre, 1:10)." (PMID 40728559, 2025). "However, research exploring the connection between COVID-19 and ON linked to antibodies against MOG Immunoglobulin G (IgG) (MOG-ON) and AQP4 IgG (AQP4-ON) is limited." (PMID 38988608, 2024). "Finally, ventral and lateral ION astrocytes in COVID-19 showed lower levels of AQP4 and MT3, respectively." (PMID 37483351, 2023). "The termination of the dynamic zero COVID-19 strategy and the subsequent resurgence of COVID-19 in China led to a marked increase in ON and provided us a chance to investigate the prevalence of serum AQP4-Ab and MOG-Ab in ON patients after SARS-CoV-2 infection." (PMID 38054007, 2023). "Together, these findings link lower AQP4 levels to increase neuroinflammation in COVID-19." (PMID 37483351, 2023). "Thus, we asked if AQP4 levels were altered in COVID-19 vs. ARDS." (PMID 37483351, 2023). "With the widespread outbreak of COVID-19, studies have reported cases of isolated ON following COVID-19 infection in patients who were seropositive for MOG-Ab and AQP4-Ab." (PMID 38988608, 2024). "Although only one relapse was observed in the COVID-19 group during follow-up, the median follow-up duration of 8 months may not be sufficient to capture the long-term recurrence patterns of MOGAD or AQP4-ON." (PMID 40728559, 2025). "Conversely, AQP4-ON was absent in the COVID-19 positive group but present in 31.4% of pre-COVID-19 patients (P = 0.075)." (PMID 40728559, 2025). "Whether COVID-19 and pregnancy/delivery interact to influence the development of MOG-ON and AQP4-ON requires further investigation with larger cohorts." (PMID 38988608, 2024). "Conversely, no causal association was observed between COVID-19 susceptibility, hospitalization, or severity and the increased risk of NMOSD, AQP4-NMOSD, or AQP4+ NMOSD." (PMID 37575255, 2023). "Following immunization with an mRNA COVID-19 vaccine the patient suffered from a severe disease exacerbation presenting as LETM which led to clinical re-evaluation and ultimately diagnosis of NMO due to detection of AQP4-autoantibodies in both serum and CSF." (PMID 35585528, 2022). "Taken together, our findings suggest that COVID-19 may be associated with shifts in the distribution of ON subtypes—particularly an increased occurrence of ADEM-ON and absence of AQP4-ON—potentially reflecting a distinct autoimmune mechanism from that of classical NMOSD." (PMID 40728559, 2025).
COVID-19 (continued). "However, none of the NMOSD patients were diagnosed with or suspected to have COVID-19 during the pandemic, regardless of whether they were AQP4-IgG seropositive or seronegative." (PMID 33828524, 2021). "In ON without COVID-19, seven (16.3%) patients were MOG-IgG-positive, 16(37.2%) were AQP4-IgG-positive, and the remaining patients were both negative." (PMID 40728559, 2025). "These trends align with our own findings in the COVID-19-positive ON subgroup, where MOG-ON accounted for 33.3% (4/12) and no cases of AQP4-ON were observed." (PMID 40728559, 2025). "The UMAPs of AQP4, F11R, and SCUBE2 demonstrate the cell type-specific distribution of these proteins, but with no significant change under the COVID-19 condition when compared to the control group." (PMID 37239234, 2023).
demyelination (17 papers, 2010 to 2025). "Antibodies against the myeline oligodendrocyte glycoprotein (MOG) and aquaporin 4 (AQP4) which are associated with CNS demyelination have been detected in some patients." (PMID 37570367, 2023). "As in MS and MOG-EM/MOGAD, ON in NMOSD was associated with prolonged P100 latencies caused by demyelination both in AQP4-IgG-positive and in mixed, AQP4-IgG-positive and AQP4-IgG-negative cohorts." (PMID 37022481, 2023). "Currently, most experts consider MOG-IgG-associated demyelination as an isolated disease entity distinct from both classic MS and aquaporin-4 (AQP4)-IgG-positive NMOSD." (PMID 31080435, 2019). "Loss of AQP4 polarity within the end-feet of astrocytes surrounding perivascular structures at the perivascular end-feet of astrocytes and diffuse AQP4 expression increases were seen in the cuprizone toxin-induced demyelination mouse model group." (PMID 36498538, 2022). "Both associated demyelinating diseases develop seizures, however, they are more common in patients with MOG antibody-associated demyelination than in patients with AQP4 antibody-associated demyelination, which is thought to be related to cortical and subcortical lesions." (PMID 34681255, 2021). "This primary mechanism of AQP4-mediated astrocytopathy offers a more parsimonious explanation than classical demyelination for the changes in our VBM-defined cerebellar gray matter ROIs." (PMID 41446878, 2025). "Next, we assessed the effect of AQP4 immunization on demyelination, which is another histopathological feature of NMOSD lesions." (PMID 36649074, 2023). "While several studies have addressed the expression and function of AQP4 during inflammatory demyelination, relatively little is known about its expression during non-autoimmune-mediated myelin damage." (PMID 32998402, 2020). "Our approach was to evaluate drug candidates that were reported to induce differentiation and/or proliferation of OPC cultures, and promote remyelination in cerebellar slices and mice following AQP4-IgG-induced demyelination." (PMID 27117475, 2016). "Diffuse increases in AQP4 expression were seen in chronic MS lesions of post-mortem human subjects and cuprizone-induced demyelination models; with authors theorising that increased AQP4 expression was a result of metabolic injury to the brain in both MS subjects and demyelination animal models." (PMID 36498538, 2022).
subarachnoid hemorrhage (17 papers, 2010 to 2025). A serious neurological disorder characterized by intracranial hemorrhage into the subarachnoid space. "Indeed, loss of perivascular AQP4 polarization has been reported in various animal models including aging, AD, traumatic brain injury and subarachnoid hemorrhage." (PMID 30867902, 2019). "In scenarios involving subarachnoid hemorrhage, AQP4 expression tends to decrease." (PMID 37695472, 2024). "In subarachnoid hemorrhage model mice, blood components such as fibrinogen are present in the EPVS, the distribution of AQP4 around blood vessels is reduced, and a neuroinflammatory response is obvious." (PMID 38270115, 2024). "However, AQP4 channels seem to be involved in the removal of water from astrocyte and in their volume recovery, which also likely explains the worsening of cerebral edema in Aqp4–/– mice in the experimental models of subarachnoid hemorrhage or permanent middle cerebral artery occlusion (MCAO)." (PMID 38818517, 2024). "Baicalin is further known to reduce the levels of AQP4, TNF-α, and IL-1β in rats with subarachnoid hemorrhage." (PMID 35764613, 2022). "Herein, systemic AQP4 inhibition using TGN-020 (TGN) paradoxically exacerbates global glymphatic dysfunction despite alleviating cerebral edema and microcirculatory dysfunction following subarachnoid hemorrhage (SAH)." (PMID 41387988, 2025). "Similarly, in subarachnoid hemorrhage (SAH) models, AQP4 appears beneficial; following SAH, rats show impaired CSF-ISF fluid exchange (glymphatic clearance), and this is exacerbated in AQP4 knockout rats, leading to worse early brain injury." (PMID 40943104, 2025). "The findings from ample experimental studies on subarachnoid hemorrhage indicate that in the acute phase of SAH, increased AQP4 expression contributes to cerebral edema, inflammation, and neuronal apoptosis, while it plays a role in exacerbating or mitigating edema depending on the stage of injury." (PMID 40564125, 2025).
amyloid (16 papers, 2015 to 2025). "Both endogenous and exogenous n3-PUFAs promote amyloid-beta clearance and reduce aggregate formation by inhibiting the activation of astrocytes, protecting against the loss of AQP4 polarization, thus reducing the chance of amyloid-related injury." (PMID 33212927, 2020). "We therefore propose that there exists another pathophysiological phase in AD which follows amyloid plaque deposition and neuroinflammation and is sensitive to AQP4 deficiency." (PMID 32398151, 2020). "n3-PUFAs promote amyloid-beta clearance and reduce aggregate formation by inhibiting the activation of astrocytes, protecting against the loss of AQP4 polarization, and therefore reduce the chance of amyloid-related injury." (PMID 33212927, 2020). "Nevertheless, loss of perivascular AQP4 polarization would impair perivascular clearance of Aβ, causing amyloid deposition within the walls of cortical and pial vessels." (PMID 26526066, 2015). "Loss of perivascular AQP4 correlates with amyloid burden and Alzheimer’s progression." (PMID 40671785, 2025). "To evaluate whether loss of perivascular AQP4 localization increases Aβ levels, we evaluated the effect of Snta1 gene deletion within the Tg2576 amyloidosis line, comparing soluble and insoluble Aβ levels by ELISA in Tg2576:Snta1−/− mice and Tg2576:Snta1+/+ littermate controls at 6 months of age." (PMID 35473943, 2022). "Slides immunostained for 4G8 antibody revealed that the AQP4 inhibitor‐treated animals exhibited the overall highest level of amyloid plaques, while the AQP4 facilitator‐treated group showed the smallest amounts of deposits on whole‐brain sagittal scans." (PMID 40329616, 2025). "Lastly, we crossed this line into a mouse model of amyloidosis (Tg2576 mice) to evaluate the effect of AQP4 localization on amyloid β levels." (PMID 35473943, 2022). "AQP4 is known to be located in perivascular astrocyte endfeet; however, AQP4 is highly expressed around amyloid plaques in the brain parenchyma." (PMID 33153499, 2020). "Using 5xFAD mice, we examined the effects of deleting AQP4 on the pathogenesis of AD after the accumulation of amyloid plaques." (PMID 32398151, 2020). "Further investigations are required to elucidate the role of AQP4 in the abnormal behavior and aggravation of epileptiform neuronal activity/convulsions, which occur after amyloid plaque deposition and neuroinflammation." (PMID 32398151, 2020). "Using an adeno-associated virus (AAV)-based approach to drive astrocyte-specific AQP4 overexpression, we recapitulate the distribution of AQP4 to astroglial fine processes and observe that this change does not impair glymphatic function or alter Aβ levels in the Tg2576 mouse model of amyloidosis." (PMID 35473943, 2022). "Thus, using 5xFAD mice, we were able to assess the implications of AQP4 after the accumulation of amyloid plaques in the parenchyma." (PMID 32398151, 2020). "Aquaporin-4 may play a role in glymphatic function, since ablation of Aquaporin-4 results in impairment of Aβ clearance mechanism and increased brain Aβ-amyloid deposition." (PMID 32357528, 2020). "Thus, AQP4 localization may become a useful target for therapies particularly designed to intervene with AD pathology prior to amyloid accumulation." (PMID 37762391, 2023). "Water exchange across the BBB is mediated by multiple pathways including the dedicated water channel AQP4, and redistribution of AQP4 has been associated with pericyte deficiency at the early stage of BBB disruption, as well as with the accumulation of amyloid deposits in AD." (PMID 33328848, 2020). "Here, we further investigated the effects of AQP4 modulation on brain Aβ by utilizing 2‐month‐old APPPS1 mice, at the age when amyloid deposition begins." (PMID 40329616, 2025). "The structural integrity of the glymphatic channels, as reported by the polarized perivascular expression of aquaporin 4 (AQP4), declines with age and more so when accompanied by amyloid pathology." (PMID 28993311, 2017).
amyloid (continued). "Using an AAV-based approach to drive AQP4 overexpression, we observe that the distribution of AQP4 to fine non-perivascular processes does not impair perivascular CSF-ISF exchange or alter Aβ deposition in the Tg2576 model of amyloidosis." (PMID 35473943, 2022). "AQP4 was found to not be directly involved in gliosis, neuroinflammation in response to amyloid plaque deposition, or cognitive function determined by T-maze test." (PMID 32398151, 2020).